GADD45A (growth arrest and DNA damage inducible alpha)
Diseases named in the same sentence as GADD45A in open-access papers (continued):
Sharing a sentence is not in itself a finding about the gene and the disease.
gastric cancer (11 papers, 2012 to 2025). A primary or metastatic malignant neoplasm involving the stomach. "Previous reports have shown PL causes cell cycle arrest in the G2/M-phase via induction of GADD45A in gastric cancer cells and G0/G1-phase arrest via elevation of CDKN1A expression in oral squamous cancer cells." (PMID 29535819, 2018). "The treatment of gastric cancer cells with LDEVs suppressed cell growth and induced apoptosis by upregulating GADD45A gene and protein expression and inducing reactive oxygen species (ROS) production." (PMID 34065193, 2021). "For instance, KLF5-activated lncRNA NEAT1 accelerated gastric cancer progression via serving as a scaffold for BRG1 to down-regulate GADD45A expression." (PMID 33931086, 2021). "The quantitative RT-PCR analysis confirmed the upregulation of GADD45A gene in three gastric cancer cell lines after LDEVs treatment." (PMID 32690102, 2020). "The anti-tumor mechanism was confirmed to correlate with the generation of ROS, which can upregulate GADD45a, resulting in gastric cancer cell cycle S-phase arrest and apoptosis." (PMID 32690102, 2020). "RNA sequencing analysis revealed GADD45A was elevated after LDEVs treatment in three gastric cancer cells, which was confirmed by quantitative RT-PCR and western blot assay." (PMID 32690102, 2020). "They found that LDEVs- treatment induced GADD45A expression in gastric cancer cells." (PMID 34065193, 2021). "In conclusion, RASSF10 is an important downstream target of RNF2 and the RASSF10/NPM/GADD45a/RNF2 feedback cascade may be used as a new biomarker for diagnosis and novel drug target for the therapy of gastric cancer." (PMID 34224728, 2021).
autoimmune disease (9 papers, 2012 to 2025). A disorder resulting from loss of function or tissue destruction of an organ or multiple organs, arising from humoral or cellular immune responses of the individual to their own tissue constituents. "For example, deletion of the Gadd45a gene in mice is associated with the development of an autoimmune disease similar to human SLE, suggesting this gene plays a vital role in SLE development." (PMID 22817640, 2012). "Indeed, GADD45a-deficient mice spontaneously develop an autoimmune disease characterized by the presence of autoantibodies against double-stranded (ds) DNA5." (PMID 34272424, 2021). "Furthermore, two single nucleotide polymorphisms (SNPs) of GADD45 have been identified as associated with autoimmune diseases, namely, the GADD45α 589GG+GC is linked with rheumatoid factor (RF), and the GADD45β -712CT genotypes are related to anti-RNP antibodies in SLE patients." (PMID 40083548, 2025). "An increase in GADD45A expression has been observed in T-cells from systemic lupus erythematous (SLE) patients, and GADD45A-/- mice spontaneously develop an autoimmune disease similar to human SLE." (PMID 30138371, 2018). "In our previous studies, we have demonstrated that Gadd45a contributes to autoimmune diseases by promoting DNA demethylation." (PMID 24082908, 2013). "CDKN1A, and GADD45a genes are, in essence, signal transducers that convert environmental and physiological stresses into various cellular stress responses including innate immunity, inflammation, and autoimmune diseases." (PMID 32695301, 2020). "However, interest in GADD45A has remained in the autoimmune diseases because it is overexpressed in CD4 T cells of SLE patients, correlating with global and site-specific DNA hypomethylation in these cells." (PMID 26330155, 2015). "The growth arrest and DNA-damage-inducible protein 45A (GADD45A) enzyme could also contribute to demethylation, especially in autoimmune diseases." (PMID 26330155, 2015).
leukemia (8 papers, 2013 to 2026). A malignant (clonal) hematologic disorder, involving hematopoietic stem cells and characterized by the presence of primitive or atypical myeloid or lymphoid cells in the bone marrow and the blood. "While this work was in progress, it was shown that Gadd45a plays a tumor suppressive role in other leukemias, such as FLT-3 and MLL-AF9 derived AML." (PMID 28086219, 2017). "Collectively, these observations are consistent with reduced disease latency and more aggressive leukemia in Gadd45a−/−/BCR-ABL mice, pointing to a potent and novel tumor suppressor role for Gadd45a in BCR/ABL driven leukemogenesis." (PMID 28086219, 2017). "Collectively our data provides first evidence that gadd45a functions as a suppressor of BCR/ABL driven leukemia and may provide a novel prognostic marker of CML progression." (PMID 28086219, 2017). "Finally, it would be of interest to explore if overexpression of Gadd45a delays leukemia development, and whether other Gadd45 proteins (GADD45B and GADD45G) either separately or in combination with Gadd45a modulate CML development." (PMID 28086219, 2017). "In acute myeloid leukemia (AML), GADD45A, a stress-responsive downstream effector of the LGR4 pathway, plays a protective role by restraining leukemia-initiating activity and enhancing oxidative defense." (PMID 41601687, 2026). "Taken together, the accelerated development of leukemia in the absence of Gadd45a cannot be explained by differences in HSCs, homing and engraftment in non-oncogene expressing cells." (PMID 28086219, 2017).
non-small cell lung carcinoma (8 papers, 2007 to 2024). A group of at least three distinct histological types of lung cancer, including non-small cell squamous cell carcinoma, adenocarcinoma, and large cell carcinoma. "In non-small cell lung cancer, the downregulation of GADD45A is regarded as an important key in the differentiation pathway." (PMID 17940512, 2007).
pancreatic cancer (8 papers, 2007 to 2023). "It has been shown that GADD45A is strongly associated with various cancers, for example, in pancreatic cancer, Sinapine thiocyanate (ST) can upregulate the expression level of GADD45A and exhibit significant proliferation inhibition in pancreatic cancer cells." (PMID 37259059, 2023). "ATM serine/threonine kinase (ATM), stratifin (SFN), and growth arrest and DNA damage 45 alpha (GADD45A), which would be activated and arrest cell cycle in response to DNA damage, were up-regulated in pancreatic cancer cells after anlotinib treatment." (PMID 33748143, 2021). "We modulated GADD45A in pancreatic cancer cells using either siRNA to knockdown or adenoviral infection to overexpress GADD45A and examined the effects on AREG and EREG expression." (PMID 28733611, 2017).
Autoimmunity (7 papers, 2012 to 2025). The occurrence of an immune reaction against the organism's own cells or tissues. "Despite this, these articles are in agreement that GADD45A appears to be a key player in autoimmunity." (PMID 34072535, 2021). "Three genes, Gadd45a, Bcl2l11, and PTEN, which are implicated in autoimmunity, were identified as miR-148a targets." (PMID 29760712, 2018). "A recent study, however, showed that GADD45a may contribute to autoimmunity by promoting DNA demethylation in lupus T cells." (PMID 22642378, 2012). "The upregulated miR-148a also targets PTEN, as well as GADD45A and BCL2L11, and it accelerates the development of autoimmunity." (PMID 30658565, 2019). "Studies have revealed that the hypomethylation of global genomic DNA and many immune-related genes in SLE CD4+ T cells result in the overexpression of growth arrest and DNA damage inducible 45 alpha (Gadd45a), CD70, CD11a, CD40L, and perforin, thereby contributing to autoimmunity." (PMID 39835138, 2024).
glioblastoma (7 papers, 2016 to 2025). The most malignant astrocytic tumor (WHO grade IV). "In IDH1R132H glioblastoma cells, miR-148a inhibitors significantly increased and miR-148a mimics significantly decreased GADD45A expression." (PMID 28445981, 2017). "In contrast to previous reports that IDH1 R132H mutations promote survival, we confirmed that miR-148a increased cell migration and invasion by downregulating GADD45A in IDH1R132H glioblastomas." (PMID 28445981, 2017). "We observed pcDNA3.1-GADD45A or GADD45A-siRNA glioblastoma cells in mouse brains in vivo by bioluminescence imaging (BLI)." (PMID 28445981, 2017). "Inhibition of miR-148a significantly reduced β-catenin, EMT marker, and MMP-9 expression in IDH1R132H glioblastoma cells and these effects were prevented by GADD45A knockdown." (PMID 28445981, 2017). "Upregulation of miR-148a only significantly increases β-catenin, MMP-9, and EMT marker expression in IDH1R132H glioblastoma cells by downregulating GADD45A." (PMID 28445981, 2017). "To determine the effect of miR-148a on GADD45A-mediated control of β-catenin, MMP-9, and EMT marker expression, we upregulated or downregulated miR-148a in IDH1WT or IDH1R132H glioblastoma cells overexpressing GADD45A." (PMID 28445981, 2017). "IDH1R132H glioblastoma cells were transfected with scrambled or GADD45A siRNA together with miR-148a inhibitors." (PMID 28445981, 2017). "Furthermore, GADD45A increased E-cadherin expression at the membrane and inhibited glioblastoma cell invasion." (PMID 28445981, 2017). "We knocked down GADD45A expression in glioblastoma cells using three different siRNAs." (PMID 28445981, 2017). "To investigate whether GADD45A inhibits expression of β-catenin, MMP-9, and EMT markers, we performed western blotting on total protein extracts from IDH1WT or IDH1R132H glioblastoma cell extracts after GADD45A overexpression." (PMID 28445981, 2017). "In this study, we confirmed that GADD45A reduced the expression of β-catenin and MMP-9 in IDH1R132H glioblastoma cells, providing a deeper insight into how β-catenin is regulated in these tumors." (PMID 28445981, 2017). "GADD45A overexpression promoted the redistribution of β-catenin from the nucleus and cytoplasm to the membrane in IDH1R132H glioblastoma cells." (PMID 28445981, 2017). "Growth arrest and DNA-damage-inducible protein (GADD45A) was downregulated and microRNA 148a (miR-148a) was upregulated in in IDH1R132H human glioblastomas tissues." (PMID 28445981, 2017). "The effect of GADD45A on glioblastoma cell proliferation was inhibited by miR-148a inhibitors and increased by miR-148a mimics in IDH1WT and IDH1R132H glioblastoma cells." (PMID 28445981, 2017). "In contrast, GADD45A overexpression increased E-cadherin expression in IDH1WT and IDH1R132H glioblastoma cells." (PMID 28445981, 2017). "GADD45A overexpression reduced the migration and invasive ability of IDH1WT and IDH1R132H glioblastoma cells." (PMID 28445981, 2017). "In vitro experiments showed that GADD45A negatively regulates IDH1R132H glioma cell proliferation, migration, and invasion, and neurosphere formation in IDH1R132H glioblastoma stem cells (GSC)." (PMID 28445981, 2017).
liver fibrosis (7 papers, 2019 to 2026). "The in vitro and in vivo data collectively suggest that EZH2 and JMJD3 coordinately modulate HSCs activation and liver fibrosis through, at least in part, epigenetically regulating Bambi, Cdkn1a, Gadd45a and Gadd45b." (PMID 33391480, 2021). "GADD45A has been also shown to exert a protective effect against hepatic fibrosis in mice." (PMID 37059745, 2023). "The therapeutic effects of DZNep as epigenetic drug in liver fibrosis are associated with the regulation of EZH2 towards direct target genes encoding TGF-β1 pseudoreceptor BAMBI, anti-inflammatory cytokine IL10 and cell cycle regulators CDKN1A, GADD45A and GADD45B, which are also regulated by JMJD3." (PMID 33391480, 2021).
lupus (7 papers, 2012 to 2021). "Polymorphisms in GADD45a and GADD45b genes and protein expression have been investigated in rheumatoid arthritis (RA) and systemic lupus erythematosus (SLE) patients." (PMID 34272424, 2021). "This study is to examine the associations of GADD45a and GADD45b genes with rheumatoid arthritis (RA) and systemic lupus erythematosus (SLE) patients." (PMID 31195707, 2019). "Next to this, it is the promotion of DNA demethylation in lupus CD4+ T cells that lead to the increased expression of gadd45A, showing that the environment and epigenetics work closely together to determine the expression of disease in an individual." (PMID 25566322, 2014). "In this study, we identified protein(s) that bind to Gadd45a, assessed their gene and protein expression and their association with CD11a, CD70 mRNA, and lupus disease activity." (PMID 24082908, 2013). "GADD45a gene knockout mice developed human like systemic lupus erythematosus (SLE)." (PMID 31195707, 2019). "Furthermore, lupus flares often occurred after exposure to UV-B irradiation, and positive correlations were found between the expression of Gadd45a and hypomethylation of CD11a/CD70." (PMID 28785369, 2017). "Additionally, studies have found that methylation status at certain genes in lupus CD4+ T cells can be removed by growth arrest and DNA damage-induced 45alpha (Gadd45a)." (PMID 28785369, 2017). "Our data demonstrate that HMGB1 binds to Gadd45a and may be involved in DNA demethylation in CD4+ T cells during lupus flare." (PMID 24082908, 2013).
lymphoma (7 papers, 2014 to 2023). A malignant (clonal) proliferation of B- lymphocytes or T- lymphocytes which involves the lymph nodes, bone marrow and/or extranodal sites. "Interestingly, the ATM−/− Gadd45a−/− mice showed higher a incidence of lymphoma and leukemia, as well as an increased rate of metastasis compared to ATM−/− mice." (PMID 24474198, 2014). "Furthermore, we also observed an increased metastasis (one case of BM infiltration and one case of spleen infiltration) in ATM−/− Gadd45a−/− mice, which indicates that Gadd45a deletion increases the degree of malignancy of lymphoma in ATM−/− mice." (PMID 24474198, 2014). "On the contrary, GADD45A overexpressed in lymphoma cells and GM did not induce changes." (PMID 25622250, 2015). "In addition, lymphoma cells was characterized by an overexpression, which was not changed by GM, of GADD45A, one of the DNA-damage checkpoint genes that, upon various kinds of stress, maintained genomic integrity in many cell types through DNA repair." (PMID 25622250, 2015).
glioma (6 papers, 2017 to 2024). A benign or malignant brain and spinal cord tumor that arises from glial cells (astrocytes, oligodendrocytes, ependymal cells). "CF-ME induced G1 phase cell cycle arrest in glioma cells, potentially mediated by upregulation of GADD45A and p21 and downregulation of CDK6." (PMID 39408228, 2024). "GADD45A expression was higher in normal tissues compared with glioma tissues and was lower in IDH1R132H glioma tissue than IDH1WT glioma (P<0.01)." (PMID 28445981, 2017). "MiR-148a promotes malignancy in these gliomas by inhibiting the tumor suppressor function of GADD45A." (PMID 28445981, 2017). "Taken together, these findings indicated that GADD45A inhibits glioma cell and GSC proliferation in vitro." (PMID 28445981, 2017). "To confirm differential expression of GADD45A and miR-148a, we measured GADD45A and miR-148a mRNA levels in the same human glioma tissues using qRT-PCR." (PMID 28445981, 2017). "Taken together, these findings show that GADD45A suppresses the effects of miR-148a in I IDH1R132H gliomas." (PMID 28445981, 2017). "Our findings demonstrated that miR-148a promotes glioma cell invasion and tumorigenesis by downregulating GADD45A." (PMID 28445981, 2017). "Taken together, these findings show that miR-148a stimulates the cellular distribution of β-catenin by inhibiting GADD45A in IDH1R132H glioma cells." (PMID 28445981, 2017). "MiR-148a expression was enhanced and growth arrest and DNA-damage-inducible protein (GADD45A) expression was reduced in human IDH1R132H gliomas." (PMID 28445981, 2017). "Furthermore, miR-148a has been shown to promote migration and invasion by downregulating the tumor suppressor gene, GADD45A, in glioma cells." (PMID 33062427, 2020). "Taken together, these findings suggested that GADD45A inhibits glioma tumorigenesis in vivo." (PMID 28445981, 2017). "GADD45A staining appeared to be stronger in normal tissues than glioma tissues." (PMID 28445981, 2017). "In addition, we found that miR-148a was upregulated in IDH1R132H glioma tissue and inhibited the tumor suppressor function of GADD45A by downregulating its expression." (PMID 28445981, 2017). "We examined GADD45A protein expression in normal and glioma tissues by immunohistochemistry." (PMID 28445981, 2017). "The expression patterns of GADD45A and miR-148a were opposite in human glioma tissues." (PMID 28445981, 2017). "This indicates that miR-148a significantly inhibits GADD45A to increase the migration and invasion of IDH1R132H glioma cells." (PMID 28445981, 2017). "In conclusion, we have demonstrated that the tumor suppressor gene GADD45A and the miR-148a are differentially expressed in IDH1R132H gliomas." (PMID 28445981, 2017). "Our findings provide novel insights into how GADD45A is downregulated by miR-148a in IDH1R132H glioma and may help to identify therapeutic targets for the effective treatment of high-grade glioma." (PMID 28445981, 2017).
osteosarcoma (6 papers, 2007 to 2025). A usually aggressive malignant bone-forming mesenchymal neoplasm, predominantly affecting adolescents and young adults. "The acute increase of GADD45A is usually associated to apoptosis in osteosarcoma, but its prolonged increase is a compensatory response to chemotherapeutic drugs and is related to the acquisition of resistance to methotrexate." (PMID 32599901, 2020). "Decitabine-induction of GADD45A expression was examined in two other osteosarcoma cell lines (MG63 and HOS), to determine the specificity of this effect." (PMID 17845729, 2007). "Consistently with these premises, the silencing of GADD45A and MYC chemosensitized Dox-resistant osteosarcoma cells, by disrupting adaptive responses functional to acquire Dox-resistance." (PMID 32599901, 2020).